YBX1 (Y-box binding protein 1)
Diseases named in the same sentence as YBX1 in open-access papers (continued):
Sharing a sentence is not in itself a finding about the gene and the disease.
gastric cancer (continued). "YBX1 binds to HOXC-AS3 to mediate the tumorigenesis of gastric cancer." (PMID 34476221, 2021). "Furthermore, knock-down of YBX1 in gastric cancer cell lines inhibits their migration, and substantially hinders tumour growth." (PMID 25980435, 2015). "Thus, the lncRNA GAS5/YBX1/p21 pathway is important for controlling cell proliferation in stomach cancer." (PMID 25959498, 2015). "Therefore, YBX1 is a key player in gastric cancer autophagy and resistance to 5-FU, and could be a potential target for overcoming resistance." (PMID 41584846, 2025). "Thus, we sought to verify whether YBX1/SPP1 mediated gastric cancer development through NF-κB signaling." (PMID 34758833, 2021). "YBX1 stabilizes the ATG9A mRNA by modifying it with m5C, boosting autophagy, which ultimately helps gastric cancer cells resist 5-FU." (PMID 41584846, 2025). "In gastric cancer, YBX1 serves as a 5mC reader and stabilizer of ORAI2 mRNA, resulting in the upregulation of E2F1, promoting peritoneal metastasis and colonization of gastric cancer." (PMID 38255791, 2024). "To further confirm the role of YBX1 and SPP1 in gastric cancer development, we assessed overall survival in gastric cancer patients with low/high expression of YBX1 and SPP1 using TCGA database analysis." (PMID 34758833, 2021). "For example, there is direct binding between Y-box binding protein-1 (YBX1) and circFAT1 (e2) from exon 2 of FAT atypical cadherin 1 (FAT1), which can inhibit the progression of gastric cancer." (PMID 34277605, 2021). "One example is the lncRNA GAS5, which interacts with YB-1 protein and activates YBX1 translation, upregulating p21 and initiating G1 cell cycle arrest in stomach cancer." (PMID 31632972, 2019). "Recently, Y-box binding protein 1 (YBX1), a transcriptional activator of p21, has been reported to interact with GAS5 lncRNA in stomach cancer cells." (PMID 26198250, 2015). "PIN1P1 was identified to directly bind to the YBX1 protein, which may mediate PIN1 upregulation and promote gastric cancer progression." (PMID 37929660, 2024). "Additionally, YBX1 induces aerobic glycolysis by activating protein expression of HIF-1α and MYC in gastric cancer cells 46-48." (PMID 38948065, 2024). "Here we found that in gastric cancer, PIN1P1 interacted with YBX1, upregulating its protein expression, which in turn enhanced the expression of PIN1, in which transcription factor E2F1 may be involved." (PMID 37929660, 2024). "Our work suggests that TAGLN2, YBX1 and induced ISGs are novel predictive markers for clinical outcomes, and that targeting TAGLN2-mediated ISG upregulation is an attractive therapeutic sensitization strategy for gastric cancer patients." (PMID 39168971, 2024). "In gastric cancer, GAS5 binds to the YBX1 (Y-Box Transcription Factor) protein." (PMID 34202777, 2021). "Our findings demonstrated that type I collagen promoted TIC-like phenotypes and chemoresistance through ITGB1/YBX1/SPP1/NF-κB pathway, which may provide novel insights into gastric cancer therapy." (PMID 34758833, 2021). "Therefore, we confirmed that 3D collagen gels stimulate elevated expression of YBX1 and SPP1 through ITGB1 in gastric cancer." (PMID 34758833, 2021). "In contrast to the previous observation that lncRNA GAS5 decreases CDK6 mRNA and protein levels in bladder cancer, our results indicate that lncRNA GAS5 knockdown reduced the YBX1 protein level without affecting its transcription in stomach cancer." (PMID 25959498, 2015). "In contrast with previous reports, we also confirmed that the ITGB1/YBX1/SPP1/NF-κB signaling axis is correlated with drug resistance development in gastric cancer, and blockade of ITGB1/NF-κB signaling led to improved anticancer effects in a subcutaneous gastric cancer mouse model." (PMID 34758833, 2021).
melanoma (58 papers, 2011 to 2025). A malignant, usually aggressive tumor composed of atypical, neoplastic melanocytes. "RBPs that were specific to EVs included YBX1, a known prognostic marker for several cancers, which has been linked to melanoma progression by regulating MIA-dependent expression." (PMID 38353833, 2024). "The expression of YBX1 was significantly up‐regulated in melanoma and negatively correlated with the overall survival of patients." (PMID 39716999, 2025). "It was found that lncRNA BASP1-AS1 can interact with YBX1, activating the Notch signaling pathway and driving migration in melanoma." (PMID 38561355, 2024). "Y-box binding protein 1(YB-1) is an unfavorable prognostic marker secreted from melanoma depending on [Ca2+] i and ATP levels, the expression of which increases in primary and metastatic melanoma, compared to benign melanocytic nevi." (PMID 37221594, 2023). "A known MIA/CD-RAP downstream mediator is the Y-box-binding transcription factor 1 (YBX1), which has been described in chondrogenesis and melanoma development." (PMID 36672165, 2023). "Y-box binding protein 1 (YB-1) is an important oncogenic protein, overexpressed in malignant melanoma with increasing protein levels during tumor progression." (PMID 39086667, 2023). "Conversely, elevated Y-box binding protein 1 secretion stimulates melanoma cell migration, invasion, and tumorigenicity." (PMID 35162934, 2022). "Y-box binding protein 1 is an unfavorable prognostic marker secreted from melanoma depending on [Ca2+]i and ATP levels, the expression of which increases in primary and metastatic melanoma, compared to benign melanocytic nevi." (PMID 35162934, 2022). "The shrimp-derived miR-S8 has been described to suppress stemness and tumor progression by degrading the mRNA of the transcription factor human Y-box binding protein 1 (YB-1) in melanoma stem cells." (PMID 33348804, 2020). "Accordingly, upon downregulation of intracellular YB-1 levels by means of RNA interference or CRISPR/Cas9 mediated YBX1 knockout, we found an impaired wound closure capacity for several melanoma cell lines (A375, MelJuso, WM115, WM266-4)." (PMID 32824741, 2020). "RNA immunoprecipitation performed in melanoma-derived SK-Mel-28 and in a patient-derived lymphoblastoid cell line indicated that YBX1 can bind the wild type p16INK4a mRNA increasing its translation efficiency, particularly during hypoxic stress." (PMID 26498684, 2015). "Y-box binding protein 1 (YBX1) is a member of the CSD (cold-shock domain) protein superfamily over-expressed in several types of cancer including melanoma." (PMID 26498684, 2015). "Several studies have indicated that the overexpression of YB-1 (Y box-binding protein-1) is related with secondary resistance to cisplatin in melanomas, breast, ovarian, and bladder cancers." (PMID 22118625, 2011). "MicroRNAs (miRNAs) have also been explored as a target for melanoma, with the results showing that miR-S8 could suppress the stemness of melanoma stem-like cells by targeting specific transcription factors, like Y-box binding protein 1 (YB-1)." (PMID 40867277, 2025). "We next detected the expression of YBX1 in melanoma by TCGA analysis." (PMID 39716999, 2025). "In addition, the expression of MLLT3 was irrelevant with YBX1 in melanoma, indicating YBX1 was not regulated by MLLT3." (PMID 39716999, 2025). "Furthermore, YBX1’s cytoplasmic activity promotes the tumorigenicity and metastatic potential of melanoma cells by facilitating EMT-like properties." (PMID 38255791, 2024). "Moreover, the LncRNA BASP1-AS1 regulates the transcription of Notch3 by interacting with YBX1 in melanoma." (PMID 37253771, 2023). "In A375 and A875 melanoma and squamous cell carcinoma A431 cells, LL-37 (at a dose of 0.05 μg/mL over 24 or 48 h) stimulated migration through the expression of Y-box binding protein-1 (YB-1) and nuclear factor-κB (NF-κB)." (PMID 35956937, 2022).
melanoma (continued). "Previously, we could show that the oncogenic cold shock domain family member Y-box binding protein 1 (YB-1; Protein Accession: P67809) is overexpressed in malignant melanoma cells with further increasing protein levels during tumour progression." (PMID 32824741, 2020). "YBX1 silencing is reported to significantly reduce MMP13 expression in melanoma cells." (PMID 31358880, 2019). "Moreover, ectopic expression of YBX1 in the SK-Mel-28 melanoma cell line was able to enhance the endogenous p16 protein level." (PMID 26498684, 2015). "We demonstrate that a germline sequence variant found in the p16INK4a 5′UTR (c.-42T>A) of a multiple primary melanoma patient results in local flexibility changes in RNA structure, impairing the binding of YBX1 and its stimulatory effect on IRES-dependent translation efficiency." (PMID 26498684, 2015). "In a recent study in melanoma, we found that YBX1 could transcriptionally regulate MIA/CD-RAP-dependent p54nrb transcription." (PMID 24349210, 2013). "Here we demonstrate that p16INK4a 5′UTR acts as a cellular IRES and we discovered YBX1 as a positive regulator of p16INK4a cap-independent translation under hypoxic stress both in cancer-derived cell lines and p16INK4a wild type lymphoblastoid cells obtained from a melanoma patient." (PMID 26498684, 2015). "The knockdown of YBX1 in melanoma cells led to a reduction in MAGEA1 mRNA levels, while overexpression of YBX1 significantly increased MAGEA1 expression." (PMID 39716999, 2025). "Although YBX1 binds to the AP-1 site in the MMP13 promoter and represses its expression in HeLA cells, shYBX1-silenced A375 melanoma cells had a significant reduction in the expression of MMP13." (PMID 36672165, 2023). "This miRNA has been found to suppress the expression of cMYC, Y-box binding protein 1 (YB1), MITF and EZH2 in melanoma." (PMID 37325482, 2023). "This is not surprising because miR-137 inhibits invasion and migration of melanoma cell lines by directly targeting oncogenes, including the transcription factors TBX3, EZH2, c-MET and Y box-binding protein 1 (YB1)." (PMID 32295074, 2020). "BASP1-AS1 recruits YBX1 to NOTCH3 promoter, driving melanoma development." (PMID 40799245, 2025). "In detail, MIA supports melanoma development through activation of the transcription factor Y-box binding protein 1 (YBX1), which in turn enhances NONO transcription." (PMID 38493226, 2024). "Furthermore, Fisetin renders melanoma tumor growth both in vitro and in vivo through inhibiting RSK kinase activity and YBX1 total protein levels, as well as the S102 phosphorylated form." (PMID 38255791, 2024). "YBX1 was reported to promote the EMT in breast, melanoma, and nasopharyngeal carcinomas." (PMID 34440660, 2021). "YBX1 drives tumorigenicity and invasiveness of melanoma cells and its expression represents a negative prognostic factor in primary melanoma patients." (PMID 32587247, 2020). "YBX1 mediates MIA/CD-RAP-dependent p54nrb (non-POU-domain-containing octamer-binding protein) transcriptional activation, with the p54nrb promoter serving as a MIA/CD-RAP-mediated regulator implicated in chondrogenesis and malignant melanoma progression." (PMID 40799245, 2025). "Interestingly, neither knockdown nor knockout of YBX1 had a direct effect on the proliferation of vemurafenib resistant melanoma cell lines." (PMID 28415756, 2017).
colorectal cancer (54 papers, 2007 to 2026). A primary or metastatic malignant neoplasm that affects the colon or rectum. "We identified that rs10890208 and rs3862218 in YBX1 were associated with colorectal cancer overall survival after chemotherapy." (PMID 35861369, 2023). "It suggested that patients with extremely high or extremely low YBX1 expression are more likely to suffer from higher colorectal cancer progression risk." (PMID 35861369, 2023). "We further estimated the association of overall survival in colorectal cancer patients receiving chemotherapy with rs10890208 and rs3862218 in YBX1." (PMID 35861369, 2023). "The association of colorectal cancer and risk genotypes of YBX1 rs10890208 and rs3862218 was illustrated by Kaplan–Meier curves." (PMID 35861369, 2023). "Higher levels of nuclear YBX1 expression in pulmonary metastasis were associated with poor outcome in colorectal cancer patients." (PMID 21170361, 2010). "We also validated the MAPK-dependent gene signature in colorectal cancers and provided evidence for the association of YBX1 with poor prognosis in colorectal cancer patients." (PMID 21170361, 2010). "Our study indicates that genetic variants in m5C modification genes may mediate changes in YBX1 mRNA levels and affect the chemotherapeutic efficacy of colorectal cancer patients." (PMID 35861369, 2023). "To further explore whether YBX1 is associated with colorectal cancer development, we analyzed the relationship between YBX1 and the colorectal cancer stage." (PMID 35861369, 2023). "It has been demonstrated that YBX1 methylation mediated by PRMT5 can regulate NF-κB activity in colorectal cancer." (PMID 41507134, 2026). "For instance, the long non-coding RNA PRKCQ-AS1 promotes the proliferation and migration of colorectal cancer cells by regulating the miR-1287-5p/YBX1 axis." (PMID 40799245, 2025). "hTERT enhances colorectal cancer proliferation and migration by recruiting YBX1 and increasing NRF2 expression." (PMID 40799245, 2025). "RP11-296E3.2 directly binds to YBX1, promoting colorectal cancer proliferation and metastasis through STAT3 activation." (PMID 40799245, 2025). "The immunohistochemistry (IHC) results demonstrated that YBX1 exhibited more intense staining in colorectal cancer (CRC) tissues compared to adjacent tissues (16 normal vs. 16 tumor, P < 0.001)." (PMID 40082414, 2025). "lnc-SOX9–4 inhibits YBX1 polyubiquitination and degradation, promoting colorectal cancer progression." (PMID 40799245, 2025). "BEZ235 is a PI3K/mTOR inhibitor that can inhibit YBX1 expression, suppress colorectal cancer cell proliferation, and promote radiation cytotoxicity both in vitro and in vivo." (PMID 38255791, 2024). "The lncRNA RP11-296E3.2 drives colorectal cancer by binding YBX1, activating STAT3 signaling, and fostering tumorigenesis and metastasis." (PMID 38255791, 2024). "In our experiment using colorectal cancer cells, we performed simultaneous RNA imaging and immunofluorescence to validate the interaction between circNFIX and YBX1." (PMID 38866007, 2024). "In colorectal carcinoma, protein arginine methyltransferase 5 (PRMT5) catalyzes methylation of the multifunctional protein Y-box binding protein 1 (YBX1) and causes NF-κB activation, which, in turn, leads to increased cell proliferation in vitro." (PMID 38279330, 2024). "In colorectal carcinoma (CRC), a specific circRNA, circNEIL3, has been identified as associated with metastasis repression by interacting with YBX1." (PMID 38255791, 2024). "Y-box-binding protein 1 (YBX1; also known as YB-1) plays a crucial role in tumor metastasis in colorectal cancer, and NEDD4L mediates YBX1 ubiquitination and degradation." (PMID 38027016, 2023). "We found that two SNPs in YBX1 were independently related to the survival of colorectal cancer patients." (PMID 35861369, 2023). "Other investigations have shown that YBX1 is highly expressed in various cancer types, including non-small cell lung cancer and colorectal cancer." (PMID 38003589, 2023).
colorectal cancer (continued). "The multifunctional protein Y-box binding protein 1 (YBX1), is a critical regulator of transcription and translation, and is widely recognized as an oncogenic driver in several solid tumors, including colorectal cancer (CRC)." (PMID 32985589, 2020). "Thirteen YBX1 targets identified in colorectal cancer cells by chromatin immunoprecipitation were also recovered in a previous study." (PMID 21170361, 2010). "To assess the role of YBX1 as a prognostic factor in colorectal cancer, we analyzed data from tissue microarrays representing 103 primary colorectal cancers and 15 pulmonary metastases by immunohistochemistry using an YBX1-specific antibody." (PMID 21170361, 2010). "To test the impact of YBX1 on CCNB1 expression in colorectal cancer cells, we transiently silenced YBX1 expression in HCT116 cells by RNA interference." (PMID 21170361, 2010). "After identifying target genes of MEK/ERK signaling and assessing the role of YBX1 in colorectal cancer cell lines, we analyzed the clinical relevance in colorectal carcinomas." (PMID 21170361, 2010). "Next we investigated the relationship between YBX1 expression and the MEK-dependent, proliferation-associated gene signature in a larger set of 43 primary colorectal cancers." (PMID 21170361, 2010). "The expression of YBX1 in primary colorectal carcinomas correlated well with the expression of YBX1 target genes including CCNB1, which are involved in cell cycle control." (PMID 21170361, 2010). "Additionally, long non-coding RNA PVT1 downregulates miR-216a-5p and inhibits the progression of colorectal cancer by regulating YBX1 expression." (PMID 40799245, 2025). "Besides, we have revealed that LINC02418 plays a significant part in the activation of Wnt pathway and promoting colorectal cancer progression via binding to YBX1 and IGF2BP1 protein to perform transcriptional and post-transcriptional regulation of CTNNB1." (PMID 40082414, 2025). "In colorectal cancer, YBX1 regulated intracellular ROS homeostasis by activating the NRF2 promoter; and such regulation might be related to ferroptosis." (PMID 39588389, 2024). "It revealed that rs10890208 and rs3862218 were eQTL for YBX1 in colorectal cancer tissue." (PMID 35861369, 2023). "Similarly, circNEIL3 recruits NEDD4L to ubiquitinate and downregulate YBX1, thereby inhibiting colorectal cancer metastasis." (PMID 38027016, 2023). "Moreover, in the TCGA database, we compared the OS between colorectal cancer with high expression levels of YBX1 and those with low levels of expression." (PMID 35861369, 2023). "PTMs on YBX1 can dynamically regulate NF-κB activity in colorectal cancers." (PMID 33375283, 2020). "About 29% of the genes in proliferation- associated clusters are up-regulated in primary colorectal cancer samples compared to matched normal tissue, demonstrating the relevance of the MEK/ERK-dependent expression signatures and the YBX1 regulator for colorectal cancer biology." (PMID 21170361, 2010). "For example, circNEIL3 directly interacts with YBX1, promoting Neural Precursor Cell Expressed Developmentally Down-Regulated Protein 4-Like (Nedd4L)-mediated proteasomal degradation of YBX1, thereby reducing its levels and inhibiting colorectal cancer metastasis." (PMID 39727969, 2024). "Therefore, the YBX1 rs10890208 and rs3862218 may predict a reduction in the overall survival of colorectal cancer patients treated with chemotherapy." (PMID 35861369, 2023). "Research has shown that in colorectal cancer patients and mouse models, the mRNA levels of NSUN5 and YBX1, as well as the total RNA m5C levels, are elevated." (PMID 40370440, 2025). "Therefore, our findings indicate that elevated YBX1 protein levels may promote colorectal cancer progression by recognizing and stabilizing oncogenic transcripts such as EREG, MAFG, and GAS6, thereby activating downstream signaling pathways involved in tumorigenesis." (PMID 40819060, 2025).